CLN3 (CLN3 lysosomal/endosomal transmembrane protein, battenin)
Description:
Mediates microtubule-dependent, anterograde transport connecting the Golgi network, endosomes, autophagosomes, lysosomes and plasma membrane, and participates in several cellular processes such as regulation of lysosomal pH, lysosome protein degradation, receptor-mediated endocytosis, autophagy, transport of proteins and lipids from the TGN, apoptosis and synaptic transmission. Facilitates the proteins transport from trans-Golgi network (TGN)-to other membrane compartments such as transport of microdomain-associated proteins to the plasma membrane, IGF2R transport to the lysosome where it regulates the CTSD release leading to regulation of CTSD maturation and thereby APP intracellular processing. Moreover regulates CTSD activity in response to osmotic stress. Also binds galactosylceramide and transports it from the trans Golgi to the rafts, which may have immediate and downstream effects on cell survival by modulating ceramide synthesis. At the plasma membrane, regulates actin-dependent events including filopodia formation, cell migration, and pinocytosis through ARF1-CDC42 pathway and also the cytoskeleton organization through interaction with MYH10 and fodrin leading to the regulation of the plasma membrane association of Na+, K+ ATPase complex. Regulates synaptic transmission in the amygdala, hippocampus, and cerebellum through regulation of synaptic vesicles density and their proximity to active zones leading to modulation of short-term plasticity and age-dependent anxious behavior, learning and memory (By similarity). Regulates autophagic vacuoles (AVs) maturation by modulating the trafficking between endocytic and autophagolysosomal/lysosomal compartments, which involves vesicle fusion leading to regulation of degradation process (By similarity). Also participates in cellular homeostasis of compounds such as, water, ions, amino acids, proteins and lipids in several tissue namely in brain and kidney through regulation of their transport and synthesis.
Synonyms: BTS; BTN1; JNCL; SLC29B1; RP101
Tractability: Antibody: UniProt places it where antibodies can reach, with high confidence; its Gene Ontology location is reachable by antibodies, with high confidence; UniProt predicts a signal peptide or a membrane-spanning region. PROTAC: ubiquitination databases record sites on it; its protein half-life has been measured.
Gene: Protein-coding gene on chromosome 16 (28,474,111 to 28,495,575, reverse strand). Ensembl gene ENSG00000188603.
Subcellular location: Lysosome membrane; Late endosome; Lysosome; Golgi apparatus; Golgi apparatus membrane; Golgi apparatus, Golgi stack; Golgi apparatus, trans-Golgi network; Cell membrane; Recycling endosome; Membrane raft; Membrane, caveola; Early endosome membrane; Synapse, synaptosome; Late endosome membrane; Cytoplasmic vesicle, autophagosome
Pathways (Reactome):
Transport of small molecules: Glycosphingolipid transport
Gene Ontology:
Molecular function: glycolipid binding; protein binding; sulfatide binding; glycolipid transfer activity; calcium-dependent protein binding
Biological process: amyloid precursor protein catabolic process; glycerophospholipid biosynthetic process; glycolipid transport; Golgi to lysosome transport; L-arginine transmembrane transport; lysosomal lumen acidification; lysosomal lumen pH elevation; negative regulation of apoptotic process; receptor-mediated endocytosis; regulation of cellular response to osmotic stress; regulation of cytoskeleton organization; regulation of fibroblast migration; regulation of protein processing; vesicle transport along microtubule; action potential; amino acid transport; associative learning; autophagosome maturation; autophagosome-lysosome fusion; ceramide transport; intracellular water homeostasis; ionotropic glutamate receptor signaling pathway; learning or memory; lysosomal protein catabolic process; lysosome organization; and 25 more
Cellular component: caveola; cytoplasm; early endosome; early endosome membrane; endoplasmic reticulum; endoplasmic reticulum membrane; Golgi apparatus; Golgi membrane; Golgi stack; late endosome; lysosomal membrane; lysosome; membrane; membrane raft; neuron projection; nucleus; plasma membrane; recycling endosome; synaptic vesicle; trans-Golgi network; autolysosome; autophagosome; late endosome membrane; cytoplasmic vesicle; cytosol; and 1 more
Genetic constraint (gnomAD): Loss-of-function variants: 49 observed, 60.83 expected, observed/expected ratio (o/e) 0.81, 90% interval 0.64 to 1.02. The upper end of that interval is the gene's LOEUF score, 1.02, which puts it in group 4 of 6, group 1 being the genes least tolerant of losing a copy. Missense variants: 515 observed, 579.41 expected, observed/expected ratio (o/e) 0.89, 90% interval 0.83 to 0.96. Synonymous variants: 255 observed, 256.16 expected, observed/expected ratio (o/e) 1, 90% interval 0.9 to 1.1.
Gene-disease validity (ClinGen):
ClinGen rates the evidence that CLN3 causes each of these diseases.
neuronal ceroid lipofuscinosis (autosomal recessive): Definitive.
Homologues: Orthologues: macaque CLN3 (97% identical), pig CLN3 (90% identical), dog CLN3 (89% identical), guinea pig CLN3 (88% identical), mouse Cln3 (86% identical), rat Cln3 (84% identical), chimpanzee CLN3 (83% identical), rabbit CLN3 (80% identical), tropical clawed frog cln3 (56% identical), zebrafish cln3 (50% identical), Caenorhabditis elegans cln-3.2 (40% identical), Drosophila melanogaster Cln3 (39% identical), and 2 more.
Diseases named in the same sentence as CLN3 in open-access papers:
CLN3 is named in the same sentence as 135 diseases in open-access papers, as found by Europe PMC text mining. Sharing a sentence is not in itself a finding about the gene and the disease. The quoted sentences say what the papers report.
Batten disease (106 papers, 2004 to 2026). "CLN3 is involved in lipid trafficking and catabolism, and mutations in this gene cause Batten disease, a group of lysosomal storage disorders characterised by progressive neurodegeneration." (PMID 41573945, 2026). "Our study provides a potential mechanism underlying the development of CLN3-mediated Batten disease at cellular level." (PMID 39917569, 2025). "Batten disease typically manifests in childhood and is marked by progressive neurological decline due to mutations in the CLN3 gene, which encodes a transmembrane lysosomal/endosomal protein needed for normal lysosomal function." (PMID 39959975, 2025). "We show here that loss of CLN3, the lysosomal protein affected in Batten disease, leads to DNA damage accumulation and pro-apoptotic signaling in human cells and in the mouse brain." (PMID 41198904, 2025). "CLN3 Batten disease is a lethal pediatric neurodegenerative disease caused by mutations in the CLN3 gene." (PMID 41189054, 2025). "Here we demonstrate that ASO-induced skipping of CLN3Δ78 exon 5 protects the retina from early functional losses in a large animal model of the most common cause of CLN3 Batten disease." (PMID 41189054, 2025). "YAP1-mediated pro-apoptotic signaling is also increased as a consequence of CLN3 functional loss in retinal pigment epithelia cells, and in the hippocampus and thalamus of Cln3Δ7/8 mice, an established model of Batten disease." (PMID 41198904, 2025). "Our findings highlight the therapeutic value of reading-frame correction in the eye and support further exploration of this approach for treating CLN3 Batten disease vision loss." (PMID 41189054, 2025). "The detection of DNA damage markers downstream of impairment of lysosomal phospholipid catabolism opens the possibility for novel disease-modifying therapeutic strategies for patients with Batten disease caused by mutations in CLN3." (PMID 41198904, 2025). "A recent paper exploring the proteomic changes in microglia with another LSD, Batten disease caused by loss of CLN3, identify similar changes to those seen here, including increased TTYH3, PTTG1IP, LAMTOR3, PSAP, STARD3NL, TSPAN7, TMEM192 and NPC1." (PMID 40608809, 2025). "Applied to the neurodegenerative lysosomal storage disorder known as Batten disease (caused by mutations in the CLN3 gene), tagless LysoIP revealed substantial accumulation of glycerophosphodiesters (GPDs) in patient lysosomes." (PMID 39959975, 2025). "The Cln3 gene encodes a protein that is involved in lysosomal function and causes a neurodegenerative disease commonly known as Batten disease." (PMID 38368171, 2024). "The Hastings group developed an exon-skipping strategy in mice to target a mutant allele that causes CLN3, a form of Batten’s disease." (PMID 39119251, 2024). "Batten disease is an autosomal recessive disorder typically affecting children between the ages of 5 and 10 caused by mutations in CLN3." (PMID 38248465, 2024). "Mouse models for Cln3 deficiency showed a relatively late onset of symptoms (6–12 mo), including several hallmarks of Batten disease such as neurodegeneration and lipofuscin accumulation." (PMID 38195117, 2024). "The juvenile onset NCL (JNCL), also known as Batten disease, is the most common presentation and is caused by mutations in the CLN3 gene." (PMID 38248465, 2024). "Mutations in CLN3 are causative of juvenile neuronal ceroid lipofuscinosis, a rare neurodegenerative disease affecting children also known as Batten disease." (PMID 36965618, 2023). "Batten disease, caused by mutations in CLN3, is one of the most devastating neurodegenerative childhood diseases." (PMID 37400440, 2023). "ABCA4-RD and Stargardt disease is confined to the retina, but CLN3-associated Batten disease is a devastating diagnosis because of the systemic and neurological manifestations that typically result in a short life expectancy." (PMID 38066771, 2023).
Batten disease (continued). "The CLN3 subtype (resulting from mutations in the CLN3 gene and referred to here as CLN3 disease) is the most common form of Batten disease in the United States and Europe, and has a juvenile onset of symptoms between 4 and 7 years of life." (PMID 37305926, 2023). "CLN3 pathogenic variants were found in seven patients, all of whom were diagnosed with Batten disease." (PMID 36011402, 2022). "CLN3 disease (also known as Batten disease or juvenile neuronal ceroid lipofuscinosis) is a lysosomal storage disorder caused by mutations in CLN3." (PMID 36453132, 2022). "TPP1 protease activity appears elevated when Batten disease is caused by mutations in CLN3 indicating a common biological pathway for CLN2 and CLN3 disease." (PMID 35159273, 2022). "It is well-known that progressive development of cardiac pathology in CLN3 Batten disease is associated with the progression of the disease." (PMID 33792748, 2021). "This type of Batten disease derives from mutations in the CLN3 gene that encodes a lysosomal membrane protein called battenin, the function of which is poorly understood." (PMID 34690692, 2021). "Cln3 has also been implicated in Dictyostelium’s osmoregulation, and osmoregulatory defects have been observed in mammalian cell models of Batten disease." (PMID 34776869, 2021). "One of the surprising facts is that so far no large animals (dogs, cows, goats, etc.)have been found to suffer from a malady similar in symptoms to Batten disease (i.e., from the mutations or deletions in the CLN3 gene)." (PMID 33137890, 2020). "CLN3 Batten disease results from homozygous mutations in CLN3, which are present in ~ 80% of individuals inflicted with Batten disease." (PMID 32601357, 2020). "These include (with the mutated gene in parentheses): juvenile neuronal ceroid lipofuscinosis (CLN3); Scheie syndrome (IDUA); aspartylglucosaminuria (AGA); Fabry disease (GLA); cystinosis (CTNS)." (PMID 32285908, 2020). "The juvenile neuronal ceroid lipofuscinosis (JNCL) or Batten disease is a devastating and fatal disorder that is connected to a mutation of the CLN3 (ceroid lipofuscinosis neuronal 3) gene." (PMID 33137890, 2020). "It was shown that ROS were significantly increased in cln3 deficient Batten disease patients fibroblasts in comparison with their appropriate controls." (PMID 33137890, 2020). "Visual failure is usually one of the more advanced symptoms in v‐LINCL; however, several cases have been reported where visual failure precedes other symptoms such as ataxia and seizures, comparable to CLN3 mutations that lead to Batten disease." (PMID 31721179, 2020). "In the CLN3 variant of Batten disease, where the delta 7/8 mutation is common and affects ~ 75% of patients, male patients display symptoms before female patients, though females ultimately progress more quickly and die prior to males." (PMID 30665444, 2019). "Batten disease is an incurable and fatal disorder that in most cases is connected to a mutation of the CLN3 gene." (PMID 30621751, 2018). "It is also worth noting that in neurons most susceptible to pathological changes in Batten disease, CLN3 is detected mainly near the plasma membrane of the cell soma, as well as in the neural extensions and synaptic terminals." (PMID 30621751, 2018). "Mutations in the CLN3 gene lead to so far an incurable juvenile-onset neuronal ceroid lipofuscinosis (JNCL) or Batten disease that starts at the age of 4–6 years with a progressive retinopathy leading to blindness." (PMID 30621751, 2018). "Juvenile CLN3 (Batten) disease, a fatal, childhood neurodegenerative disorder, results from mutations in the CLN3 gene encoding a lysosomal/endosomal transmembrane protein." (PMID 29089465, 2017). "A similar stereotypical PLR was also recorded in one case of syndromic Batten disease due to CLN3 mutations involving severe retina-wide degeneration of the outer retina." (PMID 28660274, 2017).
Batten disease (continued). "CLN3 disease, also known as Batten disease, is caused by autosomal recessive mutations in the CLN3 gene, 80–85% of which are a ~1 kb deletion." (PMID 27327661, 2016). "Mutations of the CLN3 gene cause the majority of the most prevalent, juvenile-onset, form of Batten disease, and this disorder is now called juvenile CLN3 disease to clearly identify the genetic cause and clinical form." (PMID 26035843, 2015). "That associated with mutations in the CLN3 gene gives rise to CLN3 (ceroid-lipofuscinosis, neuronal 3) which manifests with a progressive retinopathy leading to blindness, dementia, epilepsy, and motor dysfunction." (PMID 25309324, 2014). "In particular, ACP2 has been associated with progressive supranuclear palsy and ACP2 activity levels are known to be increased in juvenile neuronal ceroid lipofuscinosis, a disease caused by mutations in the lysosomal protein CLN3 (Batten disease:)." (PMID 24722417, 2014). "Mutations of the CLN3 gene cause juvenile CLN3 disease (formerly known as juvenile neuronal ceroid lipofuscinosis or juvenile Batten disease)." (PMID 23840424, 2013). "Juvenile CLN3 disease (formerly known as juvenile neuronal ceroid lipofuscinosis) is a fatal childhood neurodegenerative disorder caused by mutations in the CLN3 gene." (PMID 23840424, 2013). "Mutations in the CLN3 gene are thought to be responsible for the neurodegenerative disorder Batten disease (OMIM:204200)." (PMID 15571623, 2004). "We next focused on CLN3, a gene implicated in the neurodevelopmental disorder Batten disease." (PMID 41573945, 2026). "This novel molecular mechanism underlying the loss of CLN3 in mammalian cells and tissues may pave a way for novel c-Abl-centric therapeutic strategies to target Batten disease." (PMID 41198904, 2025). "Here, we demonstrate in human cell lines and in the brain of a mouse model of Batten disease that loss of CLN3 function causes DNA damage, which triggers a pro-apoptotic response mediated by the transcription factor YAP1, in a c-Abl-dependent and Hippo-independent manner." (PMID 41198904, 2025). "Strikingly, there are several commercially available drugs that target c-Abl, which, if effective in CLN3 loss-of-function, might constitute a therapeutic approach for Batten disease, which is currently incurable." (PMID 41198904, 2025). "We extended the sequence analysis by including additional species and highlighting the residues associated with Batten disease in human CLN3 that are conserved in the zebrafish sequence, providing a first argument in favor of zebrafish being a relevant organism for modeling this disease." (PMID 38195117, 2024). "Juvenile neuronal ceroid lipofuscinosis (or Batten disease) is an autosomal recessive, rare neurodegenerative disorder that affects mainly children above the age of 5 yr and is most commonly caused by mutations in the highly conserved CLN3 gene." (PMID 38195117, 2024). "Thus, our model recapitulates some of the pathological features associated with CLN3 Batten disease." (PMID 36965618, 2023). "Finally, another important pair of conditions that present a major diagnostic dilemma is that of early-onset Stargardt disease and CLN3-associated Batten disease." (PMID 38066771, 2023). "CLN3 mutations cause Batten disease, a devastating neurodegenerative lysosomal storage disease." (PMID 37400440, 2023). "Next, they focused on CLN3, a gene that is known to be mutated in Batten disease." (PMID 39872513, 2023). "CLN3 is classically associated with juvenile neuronal ceroid lipofuscinosis (JNCL) 3 disease (OMIM: 607042), which primarily affects the nervous system and is characterized by vision impairment, cognitive disability, movement problems, speech difficulties and seizures that develop during childhood." (PMID 33921607, 2021).